C1R (complement C1r)
Diseases named in the same sentence as C1R in open-access papers (continued):
Sharing a sentence is not in itself a finding about the gene and the disease.
tumor (35 papers, 2007 to 2026). "These particular cancer cells also activated complement pathways and secreted complements such as C1S, C1R, and C3, which facilitated the recruitment of tumor-associated macrophages (TAMs) and T cells." (PMID 38951896, 2024). "Immune infiltration analysis revealed a significant difference in the proportion of immune cells in tumor and normal tissue, and the expression levels of C1R, CCL2, and TNFRSF1A were associated with immune cell infiltration of GBM." (PMID 35726234, 2022). "In particular, tumor cells were shown to produce C1r, C1s, C4, and C3, whereas C1r and C1s were able to take over the tumor-associated macrophages-produced C1q leading to formation of the initiating C1 complex." (PMID 34572075, 2021). "While the primary function of C1R has been associated with immune response regulation, emerging research indicates that its involvement in tumor growth and progression may extend beyond immune modulation." (PMID 41489302, 2026). "In various cancers, including GBM, C1R has been shown to impact the ability of tumor cells to escape immune detection, potentially contributing to the aggressive nature of the disease." (PMID 41489302, 2026). "Tumor volume growth curves showed that C1R knockdown significantly slowed the rate of tumor volume increase (***p < 0.001), ultimately resulting in markedly reduced final tumor weights (***p < 0.001)." (PMID 41489302, 2026). "Glioblastoma in particular shows a distinct pattern with a likely tumor-specific upregulation of C3a/C3aR and downregulation of factors such as FB and C1r in the blood, suggesting a role in promoting an immune environment that is supportive of the tumor." (PMID 40867623, 2025). "Additional evidence comes from the knockdown of C1Q components C1R and C1S in cancer cell lines, which slows xenograft tumor growth in mice." (PMID 41473324, 2025). "Subsequent investigation of the hub genes of the MECRGS model at the single-cell RNA level revealed that PLOD2, C1S, and C1R were primarily expressed in tumor cells." (PMID 38951896, 2024). "It has also been found that macrophage produced C1q and tumor cell-derived C1r, C1s were assembled in clear cell renal cell carcinoma and resulted in an immunosuppressive microenvironment that promotes tumor progress." (PMID 36275687, 2022). "In clear-cell renal cell carcinoma, tumor associated macrophages produce high densities of C1q, which together with tumor cell expressed C1r, C1s, C4, and C3 initiates CP activation." (PMID 33193442, 2020). "In clear cell Renal Cell Carcinoma (ccRCC), tumor cells produce C1r and C1s and use C1q secreted by macrophages, in order to form a functional C1 complex and activate the classical pathway in IgG-containing deposits or on cell-bound pentraxin 3 (PTX3)." (PMID 33113844, 2020). "This is in concordance with a previous study that correlated the expression of C1R in cutaneous SCC (cSCC) with tumor progression, cell proliferation, and migration." (PMID 32961854, 2020). "C1R targets bearing Q115E HLA-A2 were able to induce more of the fully phosphorylated p23 form 29 of the TCR ζ chain in anti-tumour and anti-viral CTL compared to similar targets bearing wild-type HLA-A2 standardized for surface antigen expression levels." (PMID 17429845, 2007). "C1R plays an important role in immune regulation and tumor progression." (PMID 41489302, 2026). "Some studies have suggested that C1R may influence immune evasion and tumor progression by modulating the TME." (PMID 41489302, 2026). "C1R knockdown reduces tumor growth and mesenchymal characteristics." (PMID 41489302, 2026). "Then, the complex interaction between the tumor cells secreting the other components of the complement (C1r, C1s, C3, and C4), the MDSCs, and exhausted T lymphocytes leads to proliferation, increased tumor invasiveness, and neoangiogenesis, which ultimately results in tumor progression." (PMID 38339243, 2024).
tumor (continued). "We have previously shown abundant expression of the complement classical pathway C1 complex components, serine proteases C1r and C1s in tumor cells in invasive cSCCs in vivo, whereas the expression of C1r and C1s was lower in cSCCs in situ, actinic keratoses and in normal skin." (PMID 38866870, 2024). "Based on previous studies, the potential interaction between C1R and C1q we identified may indicate tumor-cell hijacking of macrophage-produced C1q to promote tumor growth." (PMID 36973268, 2023). "As tumor grades increased, the mRNA expressions of C1R, C6, C7, and CFHR3 tended to be lower." (PMID 34813686, 2022). "Also, we found that the mRNA expression of C1R, C6, C7, and CFHR3 was associated with tumor grade, while the mRNA expression of C1R, C6, and CFHR3 was associated with the cancer stage." (PMID 34813686, 2022). "In cSCC, knock-down of C1s, C1r, FB, FH and FI exerts similar effects on the tumor growth." (PMID 33113844, 2020). "Although, the prognostic relevance of C1R has not been studied in cancer; however, it is associated with tumor progression and migration, hence our data suggest a significant correlation between C1R and shorter RFS." (PMID 32961854, 2020). "Elevated expression of classical pathway components C1r and C1s has been detected in cSCC tumor cells in a culture and the expression levels of C1r and C1s determined with immunohistochemistry have been shown to correlate with tumor progression from AKs to cSCCIS and cSCC in vivo." (PMID 31331124, 2019). "In the reactive astrocytes from the tumor we identified an increased expression of immune associated genes such as CHI3L1, HLA-DRA, CD274, HLA-DRB3, CD37, as well as genes that contributed to proliferation (MKI67, ANXA2) and complement components (C1S, C1R)." (PMID 31186414, 2019). "Therefore, C1r and C1s can promote cSCC tumor progression independently of the activation of the classical pathway." (PMID 31331124, 2019). "Furthermore, knockdown of C1r and C1s suppresses growth and vascularization of cSCC xenograft tumors, and promotes apoptosis of tumor cells in vivo." (PMID 31331124, 2019). "To estimate if DNAm in C1R might also be a suitable biomarker for OS in other types of cancer, we utilized 5699 DNAm profiles of 25 different types of tumor from TCGA." (PMID 26539253, 2015). "In addition, M2 macrophages synthesize C1q, a complement component that binds to the Fc portion of anti-tumor antibodies and triggers the classical component cascade in the presence of complement components such as C1r, C1s, C4, C2, C3 and C5 produced by tumor cells." (PMID 37622111, 2023). "The results indicated that C1R exhibits specific expression patterns in different anatomical regions of GBM, with significantly higher expression in cellular tumor (CT) regions compared to leading edge (LE) and infiltrating tumor (IT) regions (p < 0.001)." (PMID 41489302, 2026). "Knockdown of C1R significantly reduces tumor growth and reverses mesenchymal characteristics in GBM cells, while exogenous TGF‐β restores C1R expression and the mesenchymal phenotype." (PMID 41489302, 2026). "C1R knockdown significantly reduced tumor growth in vivo, while exogenous TGF‐β restored C1R expression and reversed the mesenchymal phenotype in a dose‐ and time‐dependent manner." (PMID 41489302, 2026). "Complement C1r (C1R) is a crucial component of the major histocompatibility complex (MHC) class I pathway, which plays a key role in immune surveillance and tumor immunity." (PMID 41489302, 2026). "C1R expression in pseudopalisading cells around necrosis (PAN) was also significantly higher than in leading edge (LE) and infiltrating tumor (IT) regions (p < 0.001)." (PMID 41489302, 2026). "TEFT inhibits GBM progression by suppressing the TGF‐β/SMAD2/3/STAT3/C1R axis, thereby attenuating EMT and reducing tumor aggressiveness." (PMID 41489302, 2026).
tumor (continued). "Our results demonstrate the upregulation of C1R, C1S, C3, IGHM and CFB in poorly differentiated tumours, suggesting activation through the classical pathway." (PMID 40847563, 2025). "We found that CAF subtypes 0 (BTG1+ CAF), 2 (CFD+ CAF), and 4 (IGFBP7+ CAF) were more abundant in the tumor than the normal, while CAF subcluster 1 (OGN+ CAF), 3 (C1R+ CAF), 5 (MFAP5+ CAF), and 6 (SFRP4+ CAF) were more abundant in the normal than the tumor." (PMID 38686196, 2024). "C1r, C1s, C2, C3, C4b were increased in animals treated with combined radiotherapy and anti-C1-INH compared to control tumor, but the down-stream components in the classical pathway were not increased." (PMID 36717781, 2023). "The results showed that the expression levels of C1R, C6, and CFHR3 were correlated with the tumor stage of HCC patients, while the expression levels of C7 and CFP were not correlated with the tumor stage of HCC patients." (PMID 34813686, 2022). "We further studied the relationship between mRNA expression levels of C1R, C6, C7, CFP, CFHR3, and tumor stages in HCC patients by using the UALCAN database since these genes were considered to have prognostic value." (PMID 34813686, 2022). "First, although we confirmed the role of C1R in GBM across multiple datasets and cell lines, the high heterogeneity of GBM suggests significant variations among different tumor subtypes and individual patients, potentially affecting the universality of TEFT treatment and TGF‐β/C1R targeted therapy." (PMID 41489302, 2026). "Also, C1R, C6, C7, and CFHR3 presented correlations with tumor grades and cancer stage in HCC patients, while CFP presented correlations with the immune markers of tumor immune cells in HCC." (PMID 34813686, 2022). "In addition, lower mRNA expression of C1R, C6, C7, and CFHR3 were found correlated with advanced cancer stages and higher tumor grades in HCC patients." (PMID 34813686, 2022). "C1R, C2, C6, C8, MBL, CFP and CFHR were downregulated in HCC and exhibited tumour-suppressive effects; thus, they could serve as prognostic markers for HCC." (PMID 36341431, 2022). "Moreover, intraoperative local electric field application to residual tumor tissue may represent a promising strategy to maximize TEFT efficacy, particularly given the marked elevation of C1R expression in MES‐subtype tumor cores and perinecrotic regions." (PMID 41489302, 2026). "Beside complement regulators and receptors, components normally produced in the liver, as C1q, C1r, C1s, C3 and C5 are locally synthesized and deposited in different tumor types and in the stroma regardless of complement activation, being predominantly tumorigenic in the majority of cancer types." (PMID 40370471, 2025). "The results showed that the mRNA expression levels of C1R, C6, C7, and CFHR3 were correlated with the tumor grade of HCC patients, while only CFP was not correlated with the tumor grade of HCC patients." (PMID 34813686, 2022). "The amplification of genes such as COL5A1, IDO1, and GOLIM4 were in accordance with their higher expression in tumor samples, whereas no significant change of protein or phosphorylation levels was observed for genes with genomic amplification, such as CD4, CD7, LIME1, UNC93B1, C1S, C1R, or C8G." (PMID 34400640, 2021).
cancer (16 papers, 2013 to 2026). A tumor composed of atypical neoplastic, often pleomorphic cells that invade other tissues. "For all cancer types, upregulation of the C1R gene was associated with poor prognosis in pediatric cancer patients, especially in the ALL cohort." (PMID 36497424, 2022). "In pan‐cancer cohorts, C1R protein expression was significantly enriched in the HALLMARK EMT pathway (size = 193, leading edge number = 123, ES = 0.80521, NES = 2.0027, p < 2e‐10)." (PMID 41489302, 2026). "Multi‐omics pan‐cancer analysis demonstrated strong positive correlations between C1R abundance (at both protein and RNA levels) and TGF‐β signaling pathway activity across multiple cancer types." (PMID 41489302, 2026). "To further validate the association between C1R and EMT across multiple cancer types, we performed comprehensive multi‐omics analyses using pan‐cancer datasets." (PMID 41489302, 2026). "To determine the possible contributions of C1r and C3 to cancer, we investigated the alteration frequency of C1R gene using the cBioPortal database." (PMID 39254172, 2024). "They recognized a significant expression of C3 and classical pathway components (C1QA, C1QB, C1QC, C1R, C1S, C4A, and C2) in all cancer types." (PMID 38003705, 2023). "A total of 79 genes were found to have significant effects on prognosis based on their expression, and 23 genes had significant impacts on prognosis in at least two different cancer types, including C1R, RPL5, and TERT." (PMID 36497424, 2022). "In the TME of ccRCC, TAMs produce C1q, whereas cancer cells synthetize C1r, C1s, C4, and C3." (PMID 38003705, 2023). "In addition, cancer-cell-intrinsic inflammatory tumor subclusters also showed an upregulation of C1R (log2FC = 0.86), C1S (log2FC = 0.46), and C3 (log2FC = 0.48), while the corresponding macrophages showed an upregulation of C1q genes (C1QA, C1QB, C1QC)." (PMID 36973268, 2023). "Furthermore, DNAm of C1R correlates also with overall survival in several other types of cancer, but the prognostic relevance was less pronounced than in AML." (PMID 26539253, 2015). "The findings suggested that C1R may be a common prognostic indicator for a variety of cancer types." (PMID 36497424, 2022). "C3 and its active fragment C3a, downstream effectors of classical complement activation mediated by C1q/C1s/C1r, were time‐dependently increased following AZD4573 treatment, as well as PD‐L1 in KRAS‐mutant cancer cells." (PMID 39254172, 2024). "In particular, C1s/C1r are reported to degrade collagen and are involved in activation of CUB domain containing proteins that regulate many aspects of cancer progression and metastasis." (PMID 27391064, 2016). "To assess differences in effector cell activation by the cancer cells, we subsequently analyzed activation-induced degranulation of NKL and NKL/GrB-T cells upon contact with C1R-neo and MDA-MB468." (PMID 23573299, 2013).
infection (13 papers, 2012 to 2025). The state of being infected such as from the introduction of a foreign agent such as serum, vaccine, antigenic substance or organism. "BBK32, which is upregulated during vertebrate infection, can potently block activation of the classical pathway by binding to C1r." (PMID 40705830, 2025). "Next, involvement of complement genes vital in phagocytosis (C1QA, C1QB, C1QC, C1R), which play a central role in immunity, response to infection, as well as synaptic pruning, further implicate the involvement of the immune system in ASD." (PMID 36590292, 2022). "As a result of these studies, we have determined that BBK32’s adhesin and C1r inhibitory activity may play a role not only during initial stages of infection, but its ability to impair classical complement-mediated clearance after a robust borrelial antibody response has been mounted." (PMID 40705830, 2025). "Sixteen cattle complement genes, including complement C2, complement factor B (CFB), complement C1r (C1R), C1R-like, C3aR1, complement factor properdin (CFP) and complement factor I (CFI) were upregulated two- to 10.6-fold in response to the infection." (PMID 41398915, 2025). "We found two components of this system (C1R and C3AR1) as well as an inhibitor to this cascade (SERPIN1) to all be upregulated during infection in addition to the equine miR-6852-5p, which is predicted to target C1R ligand." (PMID 33430330, 2021). "Additionally, ASFV-Δ9L/Δ7R infection exhibited dramatic induction of genes important during the acute-phase response, such as IL-1A, IL-1B, IL-10, and IL-18, tumor necrosis factor alpha (TNF-α), and several members of the complement pathway (C1R)." (PMID 35867564, 2022). "In addition, the expression of c1r, c6, c1qbp and c1qtnf6 in MOS200 or MOS400 groups were higher than that of the control group before or post-infection, which revealed the activation of these genes by dietary MOS and might enhance the anti-infection immunity of M. amblycephala intestines." (PMID 36768530, 2023).
cardiovascular disease (2 papers, 2022 to 2025). "Proteins in the complement and coagulation cascades pathway were identified as causal for cardiovascular disease in MR (C1R and C1S) and mediation (18 complement-related proteins mediated the effect of PGST2D_gw and 4 complement-related proteins mediated the effect of the PGSCAD)." (PMID 40032831, 2025). "Similarly, C1R expression has been reported to be highly associated with the pathogenesis of cardiovascular disease." (PMID 36341343, 2022).
ischaemic heart disease (1 paper, 2024). "We found that potassium decreased the risk of ischaemic heart disease by reducing C1R and BDH2 expressions." (PMID 39691718, 2024).
C1R also shares sentences with these, for which no sentence is quoted: Sepsis (3 papers); Alzheimer disease (2); non-small cell lung carcinoma (2); staphylococcus aureus infection (2); acne (1); acute myocardial infarction (1); Amoebiasis (1); amyotrophic lateral sclerosis (1); angioedema (1); atherosclerosis (1); babesiosis (1); bladder cancer (1); C1Q deficiency (1); clear-cell renal cell carcinoma (1); colitis (1); dementia (1); dilated cardiomyopathy (1); endothelial dysfunction (1); glomerulonephritis (1); immune complex diseases (1); intermediate uveitis (1); lung injury (1); lupus nephritis (1); meningitis (1); multiple sclerosis (1); Mycobacterium infection (1); Nephropathy (1); pancreatic cancer (1); Parkinson disease (1); periodontal disease (1).
A further 17 diseases each share a sentence with C1R in 1 paper.